BDNF (brain derived neurotrophic factor)
Diseases named in the same sentence as BDNF in open-access papers (continued):
Sharing a sentence is not in itself a finding about the gene and the disease.
Stroke (continued). "Brain-derived neurotrophic factor (BDNF) plays important roles in brain plasticity and repair and has been shown to be involved in stroke severity, recovery, and outcome in animal models." (PMID 25470006, 2014). "We found that local overexpression of BDNF expression in the SVZ by AAV-BDNF enhanced migration of SVZ cells toward the lesioned hemisphere and induced recovery of locomotor function in stroke rats." (PMID 24312581, 2013). "We recently demonstrated that repeated intranasal delivery of cocaine- and amphetamine-regulated transcript (CART) increased BDNF expression in SVZ and enhanced behavioral recovery after stroke." (PMID 24312581, 2013). "Stem cells collected from menstrual blood demonstrate multipotency and secrete trophic factors such as VEGF, BDNF, and NT-3 in response to oxygen glucose deprivation (OGD) in an in vitro model of stroke." (PMID 25177494, 2013). "Menstrual blood-derived stem cells secrete trophic factors such as VEGF, BDNF, and NT-3 in response to oxygen glucose deprivation (OGD), an in vitro model of stroke." (PMID 24147217, 2013). "This longer oxygen cycling (treated stroke by HBO for repetitive schedules for 3 weeks) therapy orchestrated gliosis and trophic factor production (BDNF, NGF, and GDNF) and decreased harmful effects by neutrophils in the early phase." (PMID 23533308, 2013). "In the lesioned Cx1 region, a reduction of the number of BDNF positive astrocytes was noticed in response to exercise (H1 vs H2) and may contribute to the reduction of mature and proBDNF levels observed in this region in exercised stroke rats as compared to sedentary stroke rats." (PMID 22962604, 2012). "Recent studies have shown that the intracerebral injection of MSCs transfected with the BDNF or GDNF gene resulted in improved function and reduced ischemic damage in a rat stroke model of middle cerebral artery occlusion." (PMID 18060066, 2007). "Endogeneous or exogenously injected neurotrophic factors including BDNF, GDNF, CNTF and NT3 had neuroprotective effect in damaged brain including stroke." (PMID 18060066, 2007). "This study evaluated whether serum levels of mature BDNF, proBDNF, and matrix metalloproteinase-9 (MMP-9) can predict functional recovery after stroke." (PMID 41758865, 2026). "Outcomes compared included clinical efficacy, National Institutes of Health Stroke Scale (NIHSS) scores, serum levels of neurotrophic factors, brain-derived neurotrophic factor, vascular endothelial growth factor, residual stenosis, vessel reocclusion, 3-month mortality, and 1-month complications." (PMID 41731855, 2026). "Furthermore, lipid-peptide nano-assemblies and curcumin-loaded liquid-LNPs modulate pathways such as the BDNF/TrkB and CREB pathways, thereby enhancing neuronal resilience in models of stroke." (PMID 40536921, 2026). "Higher BDNF levels have been reported to be correlated with lower HDL and higher triglyceride concentrations, which might influence stroke recovery and outcomes." (PMID 39949793, 2025). "Similarly, stroke rats demonstrated paretic muscle atrophy and suppression of the FNDC5/irisin/BDNF signaling pathway." (PMID 41201499, 2025). "Clinically, 30 min of aerobic exercise at a moderate intensity, but not at a mild intensity, increases serum BDNF levels in chronic post-stroke phase." (PMID 40256392, 2025). "Our results showed that the BDNF, NGF, 5-HT, and 5-HIAA levels were upregulated after the rTMS treatment, which likely contributed to improvements in cognitive function and quality of life in the patients with stroke." (PMID 40109842, 2025). "For example, in a rodent stroke model, a PEG-based hydrogel loaded with neurotrophic factors like BDNF or NGF was injected into the lesion cavity; it gradually released these proteins over several weeks, enhancing neuronal survival and axon extension compared to the untreated lesions." (PMID 40981369, 2025).
Stroke (continued). "Moreover, Brain-derived neurotrophic factor (BDNF) plays a prime role in neurogenesis, which activates neurogenesis through the pathway in the penumbra region before and after stroke due to physical exercises." (PMID 40896700, 2025). "However, our findings suggest that acupuncture may target the key regulatory factor BDNF in brain tissue repair following stroke and inhibit the three main pathways of neuronal ferroptosis, thereby comprehensively modulating the recovery of neurological function after stroke." (PMID 40842100, 2025). "In addition, NYT, in combination with physical exercise, improved sensorimotor function by stimulating BDNF/ TrkB and NGF/ TrkA, and by activating the Akt pathway in stroke models." (PMID 40361157, 2025). "Aerobic exercise is a potent non-pharmacological intervention for post-stroke cognitive recovery, exerting benefits through synergistic mechanisms: enhanced cerebral perfusion, BDNF-driven neuroplasticity and NLRP3 inflammasome suppression." (PMID 40256392, 2025). "Numerous research findings indicate that proteins such as BDNF, GAP43, PSD95, and synaptophysin play critical roles in neurogenesis, synaptic repair, and neural plasticity, all of which are crucial for functional recovery post-stroke." (PMID 39519132, 2024). "Low-frequency TMS therapy can improve the language function of patients with non-fluent aphasia after stroke more effectively and it also promote the expression of BDNF more effectively, thereby improving nerve repair and protecting brain tissue." (PMID 38725649, 2024). "Our data suggest that astrocytes may secrete BDNF and MMP9, which promote neuron survival, synaptic plasticity and angiogenic remodeling during stroke recovery." (PMID 37744881, 2023). "A study that examined serum BDNF levels in patients with minor stroke did not report the criteria for stroke diagnosis." (PMID 37895349, 2023). "BDNF belongs to the neurotrophic factor family, which increases neurogenesis and the migration of neural progenitor cells from the SVZ, thus improving the recovery of sensorimotor function after a stroke." (PMID 37242489, 2023). "Furthermore, brain-derived neurotrophic factor (BDNF), a neurotransmitter modulator, can promote the migration and proliferation of neural stem cells, and further enhance stroke recovery." (PMID 37283739, 2023). "miR‐199a‐5p agomir in rat stroke models manifested multiple benefits, such as improving neurological deficits, reducing infarct volume, promoting neurogenesis, inhibiting Cav‐1, and increasing VEGF and BDNF, which was reversed by the miR‐199a‐5p antagomir." (PMID 37349971, 2023). "The secondary outcomes included plasma levels of brain-derived neurotrophic factor (BDNF), Corin and neprilysin (NEP) before and after medication, the modified Rankin scale, and the National Institutes of Health Stroke Scale (at onset, at discharge, 30 days, and 90 days after discharge)." (PMID 37733793, 2023). "Thanks to the ELLA instrument, also Fas, BDNF and VEGFR2 were quantified in stroke and CTRL samples, observing a slight increase in VEGFR2 concentration in stroke compared to CTRL (p = 0.05, Mann–Whitney test), while BDNF was significantly decreased in stroke patients (p = 0.044, Mann–Whitney test)." (PMID 37175644, 2023). "Also, while rTMS was reported to enhance serum levels of BDNF and cortical excitability, this may not be related to genetic variants, since very similar facilitation of cortical excitability by rTMS was found regardless of BDNF Val/Met polymorphisms in healthy subjects and stroke patients." (PMID 37596980, 2023). "For the effect of rehabilitation on plasma biomarkers in stroke patients, the meta-analysis revealed that the plasma concentrations for BDNF and VEGF did not significantly increase in the treatment group, when compared to the control group." (PMID 37731856, 2023).
Stroke (continued). "Our study also demonstrated that injection of RGD-PLT@PLGA-FE delivered BDNF, bFGF and GDNF to mice brain after stroke, which could contribute to angiogenesis and neurogenesis, and subsequently improved neurobehavioral recovery." (PMID 35642036, 2022). "Other studies in stroke models have shown that PACAP reduced p75NTR levels, regulated the activity of TrkB by increased phosphorylation, and consequently increased affinity for BDNF." (PMID 36403002, 2022). "Recently, BDNF has been focused on in CIS, especially its relationship with post-stroke mobility." (PMID 36158555, 2022). "Furthermore, the sustained release of BDNF from biomaterials has provided evidence to promote neurologic function in SCI and stroke animal models." (PMID 35214053, 2022). "Meanwhile, activities could induce the emission of neurotrophic factors, involving brain-derived neurotrophic factor (BDNF) and nerve growth factor (NGF), which could promote motor, cognitive and sensory retention in post-stroke patients." (PMID 36307774, 2022). "Determining the role of BDNF and NGF in stroke and TBI is complex and often contradictory." (PMID 35283994, 2022). "The BDNF levels did not change in relation to age, neither in the stroke patients nor the healthy controls." (PMID 35756121, 2022). "BDNF was highly upregulated in NPC-CM(M)-treated brains, indicating that the functional contribution of this neurotrophic factor in the recovering synaptic network in the stroke lesions." (PMID 35887140, 2022). "From these studies, it is clear that neurotrophins, specifically BDNF and NGF, administered directly and indirectly have a growing role in increasing neurogenesis and functional recovery after stroke and TBI and that BDNF and NGF have a synergistic role in motor learning and cognitive recovery." (PMID 35283994, 2022). "In this study, some connections, including the correlation between serum BDNF levels with diabetes–stroke patients and amantadine, were not confirmed." (PMID 36009129, 2022). "Using ultrasound combined with BDNF-loaded lipid microbubbles to treat stroke rats can safely open the BBB without damaging brain tissue and effectively deliver BDNF into the brain to enhance the concentration of BDNF and repair the damaged white matter." (PMID 36117626, 2022). "We assume that neural rehabilitation following a stroke measured with BDNF happens in an insignificant amount in the absence of additional intervention." (PMID 35287688, 2022). "It has been suggested that the BDNF expression pattern after stroke, agrees well with the neuroprotective effects of this neurotrophic factor; nevertheless, the BDNF content in the lesioned hemisphere was not inversely correlated with neuronal death severity." (PMID 35879657, 2022). "The concentration and function of BDNF might also be influenced by chronic conditions such as diabetes, 66 cancer, 67 HIV, 68 stroke." (PMID 34060728, 2022). "Finally, because the rs6265 SNP is in the BDNF prodomain/pro-peptide, the unexpected benefit of this genetic variation in TBI, stroke, and neural grafting suggests that there is likely an important role for the Met pro-peptide in neuroregeneration." (PMID 35887357, 2022). "Nevertheless, there are arguments against the contribution of brain to the circulating BDNF level because in conditions such as stroke and exercise, where the concentration of BDNF in the brain is increased, there is no change in the blood BDNF content." (PMID 36101441, 2022). "Similarly, interference with BDNF/NT-3 growth factors receptor (NTRK2) signalling can impact infarct size, neurogenesis and outcome after stroke in vivo." (PMID 36418382, 2022). "Given the abundance of preclinical research using BDNF and BDNF-enhancing therapeutics, it is notable that BDNF itself is not used as a potential stroke therapeutic in current clinical trials." (PMID 35283994, 2022).
Stroke (continued). "Moreover, aerobic exercise has been demonstrated to ameliorate neurogenesis indicated by increased expression of BDNF and DCX positive cells in the ischemic hippocampus after stroke in rats." (PMID 36203743, 2022). "MSCs may also target the site of ischemic stroke and mitigate permanent damage via brain-derived neurotrophic factor (BDNF), which could affect the regulation of calcineurin, which is a common and problematic issue in stroke pathology." (PMID 35326464, 2022). "Neurotrophic factors, such as brain-derived neurotrophic factor (BDNF) and glial cell line-derived neurotrophic factor (GDNF), are considered to be involved in the regulation of key nerve functions and neuroplasticity in stroke." (PMID 35221926, 2022). "One study has demonstrated that CREB1 is the target of miR-128 after stroke, and inhibition of miR-128 by ARPP21 leads to decreased neuronal apoptosis and promoted neurological function repair with the upregulation of CREB1 and BDNF." (PMID 35096003, 2021). "Stroke in the striatum leads to either no change in striatal BDNF levels or decreases in striatal BDNF (present data)." (PMID 32378029, 2021). "For example, a bout of exercise on a treadmill produced intensity-dependent increases in brain-derived neurotrophic factor (BDNF) and vascular endothelial growth factor (VEGF) in serum, and, to a lesser extent, insulin-like growth factor 1 (IGF-1), in stroke patients." (PMID 33917909, 2021). "Our study confirmed a significant negative association between BDNF and NIHSS; both measured at the acute stroke phase." (PMID 33809965, 2021). "MiR-124 was higher in stroke patients and presented significant negative correlation between BDNF concentrations." (PMID 32944919, 2021). "The effect of PDE10A inhibition on BDNF induction only in the stroke striatum, and not the contralateral side in the present data, likely is due to the damage from the stroke." (PMID 32378029, 2021). "Stroke patients with SLC6A4 hypermethylation might have reduced 5-HTT function and 5-HT availability, which would lead to decreased BDNF expression and thus suppress neurogenesis and promote inflammation." (PMID 33526821, 2021). "Striatal stroke + 3.0 mg/kg of TAK-063 significantly induced BDNF in ipsilateral, but not contralateral striatum." (PMID 32378029, 2021). "In striatal stroke, TAK-063 induces BDNF levels in the injured striatum, such that they are boosted from the low post-stroke state to that seen in control, non-injured striatum." (PMID 32378029, 2021). "A statistically significant negative correlation between NIHSS and BDNF levels during the acute phase of stroke was noted (COR: −0.3013, 95%CI: (−0.4725; −0.1082), z = −3.01, p = 0.0026)." (PMID 33809965, 2021). "Other studies supported the lack of correlation between serum BDNF levels and lesion size or recovery in stroke patients." (PMID 31768951, 2020). "Furthermore, the activation of the BDNF/TrkB/CREB pathway has been reported to contribute to the reduction in cerebral ischemic injury and improvement in functional recovery after stroke." (PMID 32670026, 2020). "Given that BASP1 is similarly upregulated after stroke, its increase may also be mediated by NGF and BDNF." (PMID 33015061, 2020). "Thus, to confirm causal relationships between motor function and tract-related FA according to the BDNF genotype following stroke, further study is needed using regression analysis, including DTI data before the stroke." (PMID 33029116, 2020). "A low AUC of BDNF during the OGTT was an independent predictor for the composite endpoint of nonfatal MI, nonfatal stroke, and all-cause mortality in angina patients during a median follow-up of 4.4 years." (PMID 32679912, 2020). "PACAP also upregulated the brain expression of 15 genes not affected by stroke such as NEUROD1 or BDNF but known to promote synaptic plasticity and which contribute to improve functional recovery." (PMID 33551991, 2020).
Stroke (continued). "They found no change in post-stroke infarct volume, however, IN delivery of BDNF rescued neurons and altered the neuroinflammatory profile." (PMID 33233734, 2020). "Furthermore, both before and after stroke, a high proportion of BDNF positive cells were also positive for AT2R implying that AT2R signalling is involved in BDNF release." (PMID 33059037, 2020). "Our main finding is that the AUC of BDNF during a 2-h OGTT was predictive of the composite endpoint of nonfatal MI, nonfatal stroke, and all-cause mortality during a median follow-up period of 4.4 years in subjects with angina." (PMID 32679912, 2020). "Zhang and Pardridge similarly fused their anti-rat TfR Ab, OX26, to brain derived neurotrophic factor (BDNF) and have also demonstrated brain uptake in rats with middle cerebral artery occlusion, and simultaneously reduced stroke volumes in their test subjects." (PMID 32422973, 2020). "However, this is a “proof of concept” study, opening the door to further larger studies aimed at evaluating a possible correlation between the severity of strokes with miRNAs and/or VEGF-A/BDNF." (PMID 33076256, 2020). "In conjunction with our study, these findings support the potential of BDNF to facilitate recovery of cognitive function in humans, not only after stroke but also with normal ageing." (PMID 31191635, 2019). "Meanwhile, another study indicated that increased BDNF expression following stroke was not due to upregulated transcription, but rather increased uptake of the protein by astrocytes." (PMID 31105589, 2019). "In addition, a recent study suggested the potential involvement of microglial BDNF and GDNF as facilitators of post-stroke neuronal rewiring." (PMID 31105589, 2019). "No significant changes were observed in BDNF, one of the downstream targets of eNOS, between genotypes either in sham or in stroke groups." (PMID 29411514, 2018). "Indeed, induction of very delayed rPostC resulted in significantly increased concentration of growth factors such as VEGF and BDNF, which were increased by 172 % (BDNF) and by 147.8% (VEGF), 3 months after stroke induction." (PMID 30420796, 2018). "While a strong case can be made for BDNF in particular with multiple citations supporting its role, neutralising BDNF did not completely abolish post-stroke recovery." (PMID 29768965, 2018). "To determine whether the expression and maturation of BDNF were affected by TST and 5-Aza-dC treatment and enhanced contralateral neuronal plasticity after stroke, we immunoblotted protein extracts from contralesional cortical tissues." (PMID 29997355, 2018). "Given the lack of studies evaluating post-stroke BDNF concentration following physical exercise in humans, these conclusions are based on animal work." (PMID 30210424, 2018). "Out of these, 7334 articles were excluded primarily because they did not involve BDNF measurements or were evaluated BDNF levels in other conditions, rather than stroke." (PMID 30210424, 2018). "Although this study does show relevant information regarding the effect of aerobic exercise training on BDNF concentrations post stroke in humans, the intensity of training was not described in the study." (PMID 30210424, 2018). "Higher levels of BDNF were observed in the NAM-treated and NAM+ANA-12-treated groups than in the NAM+FK866-treated and saline-treated groups at 14 d after induction of the experimental stroke." (PMID 28656112, 2017). "Therefore, activated VEGF and BDNF-AKT/mTOR pathway played important roles in angiogenesis and neurogenesis post-stroke." (PMID 27465579, 2016). "It seems that training could increase the release of the same neurotrophic factors (BDNF and VEGF) in both elderly and stroke people that mediate beneficial neuroplasticity in brain areas involved in cognitive functions." (PMID 27445801, 2016).